SAMD9 (sterile alpha motif domain containing 9)
Diseases named in the same sentence as SAMD9 in open-access papers (continued):
Sharing a sentence is not in itself a finding about the gene and the disease.
cancer (10 papers, 2009 to 2025). A tumor composed of atypical neoplastic, often pleomorphic cells that invade other tissues. "Another cellular protein associated with the regulation of MYXV replication in human cancer cells is SAMD9, an interferon regulated protein, targeted by MYXV protein M062, a functional homolog of the C7L family of host range proteins from orthopoxviruses." (PMID 31936317, 2020). "In addition to Fos, some other genes associatedwith cancer, such as Anxa1, Samd9, Tppp3, Slc22a3, and Ly6d, were differently regulated in both or one of the GX-rich groups,compared with the control group." (PMID 38343302, 2024). "Besides anti-viral replication function, SAMD9 was implicated to control cancer cell death induced by inactivated Sendai virus particle (HVJ-E) or interferon (IFN) treatment, although the mechanism remains unclear." (PMID 26901061, 2016). "Knockdown of SAMD9 increased the proliferation and invasiveness of cancer cells, whereas SAMD9 overexpression reduced cell proliferation and motility." (PMID 19691856, 2009). "Here, we report that SAMD9 high expression is closely associated with the postoperative recurrence in ESCC and that SAMD9‐overexpression promotes the tumorigenicity and metastasis of ESCC cells by stimulating cancer stemness, angiogenesis, and EMT." (PMID 36757050, 2023). "Silencing MYH9 also inhibited SAMD9‐induced cancer stemness, angiogenesis, and EMT in ESCC cells." (PMID 36757050, 2023). "In contrast, shRNA knocking down SAMD9 downregulated these cancer stemness markers." (PMID 36757050, 2023). "A few genes on chromosome 7 that may play a crucial role in the disease pathogenesis and phenotype of cancers are EZH2, KMT2A, SAMD9, SAMD9L, and CUX1." (PMID 39463522, 2024). "In addition, we demonstrated that SAMD9 stimulates MYH9 expression, cancer stemness, angiogenesis, and EMT by activating the β‐catenin pathway." (PMID 36757050, 2023). "The intracellular signaling pathways that regulate MYXV replication in human cancer cells identified so far include: Protein kinase B (also known as Akt), Protein kinase R (PKR), Sterile alpha motif domain containing 9 (SAMD9), and various host DEAD-box RNA helicases." (PMID 31936317, 2020).
genetic disease (3 papers, 2020 to 2025). "Most of these genetic disorders arise from germline gain-of-function mutations in SAMD9 or SAMD9L, which lead to excessive translational repression, thus disrupting normal cellular growth and functions." (PMID 41359666, 2025). "Whilst SAMD9-associated conditions provide a fascinating model for the dynamic evolution of genetic disease, the exact mechanism by which SAMD9 regulates cell growth and mediates a cellular effect is yet to be fully established." (PMID 38434662, 2023).
SAMD9 also shares sentences with these, for which no sentence is quoted: ataxia-pancytopenia syndrome (4 papers); Fanconi anemia (4); IMAGe syndrome (3); intrauterine growth restriction (3); anemia (2); Ataxia (2); deafness (2); dyskeratosis congenita (2); primary adrenal insufficiency (2); Shwachman-Diamond syndrome (2); Thrombocytopenia (2); acute myeloid leukemia (1); aplastic anemia (1); Ataxia - pancytopenia (1); Autoimmunity (1); breast carcinoma (1); degenerative diseases of the nervous system (1); developmental delay (1); Diamond-Blackfan anemia (1); dysautonomia (1); endocrine disease (1); Familial dysautonomia (1); familial tumoral calcinosis (1); gastric cancer (1); gastrointestinal disorder (1); growth disorders (1); hematological disease (1); hemorrhage (1); hepatocellular carcinoma (1); hypothyroidism (1).
A further 14 diseases each share a sentence with SAMD9 in 1 paper.